BRCA1 (BRCA1 DNA repair associated)
Diseases named in the same sentence as BRCA1 in open-access papers (continued):
Sharing a sentence is not in itself a finding about the gene and the disease.
breast cancer (continued). "We recommend the prioritization of BRCA1-c.211dupA screening in high risk breast cancer families originating from the North-East of Tunisia." (PMID 33240314, 2020). "Overall, only few genetic studies aiming to analyze BRCA1/2 germline mutations among unselected young breast cancer patients have been reported." (PMID 32894085, 2020). "Evidence of subtype-specific PRS was also reported, with a PRS weighted for ER-negative risk displaying the strongest association with breast cancer risk in BRCA1 carriers." (PMID 32066492, 2020). "Although some genes have been identified and the pathogenic mechanism of BRCA1/2 genes for breast cancer has partly explained, the closely related genes to BRCA1/2 in breast cancer remain to be fully elucidated." (PMID 31998560, 2020). "To date, several studies have utilized different types of assays to evaluate the radiosensitivity in BRCA1/BRCA2-associated breast cancer patients compared to sporadic one and healthy individuals." (PMID 33013205, 2020). "The estimated risk of developing male breast cancer associated with mutations in the BRCA1 gene is 1% to 5%." (PMID 32934847, 2020). "In this review we provide a succinct and comprehensive overview of the surgical and systemic treatment options for patients with BRCA1/2 mutation related breast cancer and an update on the most recent systemic treatment advances." (PMID 33194613, 2020). "The most common germline mutated DDR genes in primary PCa or CRPC are found in the Breast Cancer 1 and 2 (BRCA1 and BRCA2) genes." (PMID 31197228, 2020). "Among early onset breast cancer patients who were diagnosed before 35 years of age, prevalence of germline variants in BRCA1, BRCA2, and other genes was 9.8%, 17.1%, and 4.9%, respectively." (PMID 33067557, 2020). "BRCT and RING are implicated in the interaction between BRCA1 and other proteins and their mutations are found in breast cancer." (PMID 32013256, 2020). "A total of 41 female breast cancer individuals at high genetic risk, sixteen with a BRCA1/2 pathogenic variant and twenty five controls were included." (PMID 32727387, 2020). "Hereditary breast cancer accounts for 5-10% of all breast cancer cases, and pathogenic variants in the BRCA1/2 genes have been detected in approximately 90% of hereditary breast cancer cases." (PMID 33291081, 2020). "Patients with BRCA1-associated breast cancers are younger than those with the BRCA2 mutation and those without mutation." (PMID 32322271, 2020). "In this study, we describe the clinical, pathological, and genomic characteristics of Korean breast cancer patients with germline mutations of both BRCA1 and 2 based on a single-center experience." (PMID 32455662, 2020). "On the other hand, the onset age of breast cancer from BRCA2 carriers is 10 years older than that of breast cancer from BRCA1 carriers and is highly associated with estrogen receptor (ER) positive breast cancer." (PMID 33167385, 2020). "A recent study assessed the efficacy of 13 different PARPis in the treatment of 12 different breast cancer cell lines that are either wild type or mutated for BRCA1/2." (PMID 32605126, 2020). "Although only 5 to10% of breast cancer cases in women can be ascribed to BRCA1 or BRCA2 mutations (with BRCA1 mutations slightly more common than BRCA2 mutations), impacts of the gene mutation on carriers is more profound." (PMID 32070378, 2020). "The cumulative risk of breast cancer at age 80 is estimated at 72% for BRCA1 carriers and 69% for BRCA2 carriers, while for ovarian cancer it is estimated at 44% for BRCA1 carriers and 17% for BRCA2 carriers." (PMID 32025337, 2020). "Additional interest in OPG in breast cancer has been stimulated by the tumor-promoting role of its binding partner RANKL in association with BRCA1 gene mutations." (PMID 32318347, 2020).
breast cancer (continued). "In the last decade of the twentieth century, 2 major predisposing genes susceptibility to breast cancer, BRCA1 and BRCA2 were identified through the genetic linkage mapping and the positional cloning." (PMID 32080114, 2020). "Synchronous bilateral breast cancer patients with bilateral ER inconsistency had a very low frequency of BRCA1/2 mutations (5.6%)." (PMID 32117708, 2020). "A mutational signature associated with defective HR was first identified in BRCA1/2 germline mutant breast cancers, and later in ovarian, pancreatic, and gastric cancers." (PMID 32974031, 2020). "Development of PARP inhibitors (olaparib, rucaparib, niraparib, and talazoparib) provides a promising new strategy to target homologous repair‐deficient TNBC breast cancer due to its dysfunctional BRCA1 status." (PMID 33231937, 2020). "Over the years, the K14cre; Brca1F/F; p53F/F mouse model of hereditary breast cancer has proved to be a useful tool to study tumor response and acquired therapy resistance of BRCA1-deficient breast cancers." (PMID 32053991, 2020). "Early age at diagnosis of breast cancer is a known risk factor for hereditary predisposition and some studies show a high risk of contralateral breast cancer in BRCA1 carriers diagnosed at very young ages." (PMID 32045981, 2020). "Around 10–20% of ovarian cancer and 6% breast cancer overall are caused by inheritable BRCA1/BRCA2 PVs18." (PMID 33020566, 2020). "Knowledge of germline BRCA1 or BRCA2 variant status results in increased breast cancer surveillance, earlier breast cancer diagnosis, increased gynecological cancer surveillance, and prevention of fallopian tube and ovarian cancers." (PMID 32028617, 2020). "Heterozygosity for a certain KL gene variant (KL-VS) is associated with an even higher breast cancer risk of patients with BRCA1 mutation prone to developing breast cancer." (PMID 33520985, 2020). "BRCA1 mutated breast cancer is known to be triple-negative breast cancers (TNBC), characterized by negative estrogen receptor (ER), progesterone receptor (PR), and human epidermal growth factor receptor 2 (HER2)." (PMID 33013205, 2020). "Hereditary breast cancer can account for 5 to 10% of all breast cancer patients, and BRCA1/BRCA2 mutations can be detected in more than 60% of hereditary breast cancer patients." (PMID 32944243, 2020). "Methylation was positive in 82.6% of the sporadic breast cancer patients with the loss of BRCA1 protein expression." (PMID 32856871, 2020). "By the age of 80, the estimated risk for breast cancer for women with germline BRCA1 or BRCA2 mutations is around 80%." (PMID 32053991, 2020). "In particular, a BRCA1-associated DNA methylation signature has been identified in the peripheral blood and an attempt has been made to assess the pathogenicity of BRCA1 unclassified genetic variants in breast cancer using DNA methylation profiling." (PMID 32483276, 2020). "The PARP inhibitors olaparib and talazoparib have been approved by the FDA as single agents for the treatment of metastatic breast cancer with the BRCA1/2 (breast cancer 1/2) germline mutation." (PMID 32555285, 2020). "There also was evidence of association of RAD52 S346X with reduced breast cancer risk for BRCA1 carriers." (PMID 32175645, 2020). "Preclinical studies evaluating the receptor activated nuclear factor kappa-B ligand (RANKL) on breast cell proliferation, have shown that RANKL driven progesterone signaling can play a critical role in breast cancer tumorigenesis among BRCA1 mutation carriers." (PMID 33014209, 2020). "The effect of risk-reducing salpingo-oophorectomy (RRSO) on breast cancer risk for BRCA1 and BRCA2 mutation carriers is uncertain." (PMID 31948486, 2020).
breast cancer (continued). "It is known that germline mutation of BRCA1 is a risk factor for ovarian and breast cancer and BRCA1 carrier is sensitive to drugs that targeted the DNA damage and repair pathway." (PMID 32405341, 2020). "Patients with BRCA1 or BRCA2 mutations have up to a 40% cumulative risk of contralateral breast cancer (CBC) 20 years after initial diagnosis." (PMID 32918537, 2020). "Similar to the role of mutations in BRCA1/2 in the development of breast cancer and ovarian cancer, various studies have shown that inactivating BRCA1/2 mutations, predominantly BRCA2, increase predisposition to PCa." (PMID 31197228, 2020). "Reliable estimation of the association between uptake and timing of RRSO and breast cancer risk is critical for informing counselling and clinical management of BRCA1 and BRCA2 mutation carriers." (PMID 31948486, 2020). "Specifically, BRCA1 carries with a PRS in the 10th percentile of risk distribution had a 56% chance of developing breast cancer by age 80 years." (PMID 32066492, 2020). "In a study of 236 Ashkenazi Jewish women with breast cancer, one of three founder BRCA1/BRCA2 variants was found in 25% of early-onset breast cancer cases (diagnosed under 45 years of age) and 18.5% of women diagnosed after 45 years of age17." (PMID 32300229, 2020). "We analyzed the association of germline genetic variants with the overall survival after the first primary breast cancer diagnosis in carriers of pathogenic BRCA1 or BRCA2 variants, using Cox regression." (PMID 32964118, 2020). "The FA pathway constitutes a part of the DNA-damage network, including breast cancer-susceptibility proteins BRCA1 and BRCA2." (PMID 32708070, 2020). "We studied germline genetic variants associated with the survival of breast cancer patients carrying pathogenic variants in the high-risk BRCA1 and BRCA2 genes." (PMID 32964118, 2020). "Published data had shown that 5–10% of breast cancer is hereditary and mostly related to BRCA1 or BRCA2 gene mutations." (PMID 32733560, 2020). "PARPi induce synthetic lethal effects in cancer cells lacking functional HR38 and are currently approved for the treatment of ovarian and breast cancer with BRCA1/2 mutations." (PMID 33299649, 2020). "We have previously shown in estrogen receptor (ER)-positive breast cancer cell lines that IGF-I promoted lipogenesis by reducing the association between BRCA1 and the inactive, phosphorylated form of ACCA, resulting in de-phosphorylation of the enzyme." (PMID 33212987, 2020). "In this paper we discuss the ethical aspects of genetic testing for an increased risk of breast cancer with a special focus on the ethical differences between screening for pathogenic variants in BRCA1/2 and a seven gene panel." (PMID 33087101, 2020). "Upregulation of Abcb1a/b genes encoding p-glycoprotein transmembrane efflux pumps has been shown to increase resistance to the PARP inhibitor, AZD2281, in a BRCA1 deficient mammary tumor model." (PMID 32180937, 2020). "The histology of breast cancers in women predisposed by BRCA1 and BRCA2 mutations differs in several ways." (PMID 32411603, 2020). "The second clinical trial relied on the use of Talazoparib for breast cancer patients positive for BRCA1/2 pathogenic mutations with either locally advanced or metastatic cancers (EMBRACA)." (PMID 32823908, 2020). "In our study, more than 2% of the patients carried pathogenic variants in genes other than BRCA1/2, supporting the need of using multigene panel testing in breast cancer patients in China." (PMID 32318955, 2020). "The purpose of our study was to determine the frequency of BRCA1 promoter hypermethylation and its association with expression changes of BRCA1 and main morphological features in sporadic breast cancer." (PMID 32856871, 2020). "Germline pathogenic alterations in the breast cancer susceptibility genes 1 (BRCA1) and 2 (BRCA2) are the most prevalent causes of hereditary breast and ovarian cancer (HBOC)." (PMID 32655641, 2020).
breast cancer (continued). "Cisplatin preferentially kills BRCA1-deficient breast cancers compared to BRCA1-proficient cancers; however, the inhibition efficiency is always compromised when cancers gain various additional alterations." (PMID 32591500, 2020). "For example, BRCA1-deficient tumors treated with the PARP inhibitor Olaparib developed drug resistance in vivo in a murine model of BRCA1-associated breast cancer." (PMID 32664329, 2020). "Epidemiological data on TNBC revealed its higher prevalence among women of African ancestry, young BC patients and patients with Breast Cancer Gene-1 (BRCA-1) mutations." (PMID 32564262, 2020). "In our current study, in addition to the sanger sequencing analysis, and after screening for pathogenic BRCA1/2 mutations among 17 breast cancer patients by NGS." (PMID 33240314, 2020). "We report here for the first time in Senegal, a recurrent pathogenic variant of the BRCA1 gene, c.815_824dup10 involved in the predisposition to hereditary breast cancer." (PMID 32025337, 2020). "Women with a deleterious mutation in the BRCA1/2 genes face a lifetime risk (penetrance) of developing breast cancer (BC) in the order of 55%, compared to 12% in the general population, and of developing ovarian cancer (OC) in the order of 16–59%." (PMID 33322597, 2020). "For pathogenic variants in BRCA1, the cumulative risk by age 70 years is 44–75% for breast cancer and 43–76% for ovarian cancer." (PMID 33081408, 2020). "Using data from The Cancer Genome Atlas (TCGA) for 1101 breast-cancer patients, we identified individuals with a germline mutation, somatic mutation, homozygous deletion, and/or hypermethylation event in BRCA1, BRCA2, and 59 other cancer-predisposition genes." (PMID 32997669, 2020). "Kotsopoulos and collaborators designed a case-control study recruiting 48 cases matched with 96 controls, to evaluate the impact of a panel of 14 micronutrients on breast cancer risk in women carrying the BRCA1 mutation." (PMID 32085420, 2020). "In a word, our study will help explain the underlying mechanisms of BRCA in carcinogenesis, identify novel diagnostic indicators for breast cancer and BRCA1/2-mutant breast cancer, and provide new targets and strategies for personalized therapy." (PMID 31998560, 2020). "In this review, we analyze the published data on fertility treatments and their association with primary ovarian and breast cancer risk and risk for recurrence in BRCA1/2 mutation carriers." (PMID 32719921, 2020). "Study designs were different and only one of the studies included BRCA1/2 mutation carriers already diagnosed with breast cancer." (PMID 32719921, 2020). "Nearly 50% of all hereditary breast cancer cases are due to germline mutations in the BRCA1/BRCA2 genes and are associated with early-onset breast cancer." (PMID 33067490, 2020). "In this cohort, the proportion of young women with breast cancer before the age of 35 years was lowest for both BRCA1 and BRCA2 mutation carriers (14.1 and 8.2%, respectively)." (PMID 32140806, 2020). "The phase 1 trial, consisting of 18 BRCA1/2-mutated advanced breast cancer patients receiving talazoparib monotherapy (1 mg QD), demonstrated 86% clinical benefit rate with 50% response rate at 24 weeks (median PFS 34.6 weeks)." (PMID 32883316, 2020). "This study aims to identify the gene expression profiles and interaction networks influenced by BRCA1/2 mutations, so as to reflect underlying disease mechanisms and provide new biomarkers for breast cancer diagnosis or prognosis." (PMID 31998560, 2020). "Earlier studies show that mutation in BRCA1 gene increases the risk for developing early-onset and bilateral breast cancer." (PMID 32856854, 2020). "In contrast, the dually-labeled tumors derived from CST cells and host stroma show complete response to cisplatin treatment, a first-line therapy of BRCA1-mutated breast cancers." (PMID 32053991, 2020).
breast cancer (continued). "Patients with loss-of-function of the BRCA1 or 2 proteins have a higher cumulated breast cancer risk, with a cumulated lifetime risk at eighty years old of 72% (BRCA1) and 69% (BRCA2)." (PMID 33302444, 2020). "This is particularly evident regarding hereditary breast cancer, which reportedly comprises ≈5% of all breast cancer presentations, and where BRCA1 and 2 mutations put an individual at higher individual risk of additional cancers." (PMID 32577939, 2020). "The cumulative incidence of breast cancer by age 70–80 years in female mutation carriers is 71.4–87% for the BRCA1 mutation and 77–88% for the BRCA2 mutation." (PMID 32322271, 2020). "The object of the trial is to evaluate the presence or disappearance of cytological atypias and the level of biomarkers characteristic for breast cancer in healthy women with BRCA1 or BRCA2 gene mutation or in premenopausal women." (PMID 32471217, 2020). "Due to interrupted HR repair in BRCA1-deficient breast cancer cells, DNA double-strand breaks (DSBs) in these cells can be repaired only by the nonhomologous end joining (NHEJ) pathway." (PMID 32370233, 2020). "In breast cancer, pioneering work in risk prediction, modelling genetic susceptibility based on two genes, BRCA1 and BRCA2, has been expanded to the use of polygenic scores, which have improved predictive ability." (PMID 32423490, 2020). "Recent studies have shown that the breast cancer type 1 susceptibility protein gene (BRCA1) and breast cancer type 2 susceptibility protein gene (BRCA2) germline mutations are major causes for cancer predisposition in families with a history of breast cancer." (PMID 33180852, 2020). "In the current study, beyond the recurrent founder c.211dupA mutation, a novel private BRCA1 mutation, c.2418dupA, was identified in a breast cancer patient from the North-East of Tunisia, using targeted gene sequencing." (PMID 33240314, 2020). "The meta-analysis of the cohort studies, however, showed an increase in breast cancer risk associated with use of OC in BRCA1 mutation carriers (ES = 1.59; 95% CI 1.32–1.92)." (PMID 32140806, 2020). "Of interest, such scars are also observed in tumors deficient for the breast cancer genes BRCA1 and BRCA2 (COSMIC mutational signature ID6)." (PMID 32330130, 2020). "Out of 10 other human breast cancer genes, BRCA2 (and BRCA1) stood out as contributing to the risk of canine mammary tumors in the English springer spaniel." (PMID 32005245, 2020). "Up to half of the heritable mutations in breast cancer (BC) are attributed to BRCA1 and BRCA2 genes." (PMID 32102521, 2020). "Approximately 10% of all breast cancer (BC) cases are familial and caused by inheritance of mutant BRCA1, BRCA2, or some other genes from the same DNA reparation pathway." (PMID 32164353, 2020). "Women carriers of pathogenic variants (mutations) in the BRCA1/2 genes face a high lifetime risk of developing breast cancer (BC) and/or ovarian cancer (OC)." (PMID 33266155, 2020). "Our findings are in agreement with previous studies reporting that breast carcinomas in BRCA1 mutation carriers are associated with aggressive tumor characteristics." (PMID 33240314, 2020). "The cumulative risk of developing breast cancer (BC) to the age of 80 years for heterozygotes of BRCA1 and BRCA2 pathogenic variants (hereafter, heterozygotes), has been approximated at 72% (95% CI 65–79%) and 69% (95% CI 61–77%), respectively." (PMID 32375709, 2020). "Breast carcinoma is the most common malignancy arising in female patients with HBOC as a result of germline BRCA1/2 mutations." (PMID 33117676, 2020). "Germline mutations in the tumor suppressor gene BRCA1 account for the largest proportion of BC susceptibility to date and confer a 55–65% lifetime risk of developing breast cancer." (PMID 33087180, 2020).